RASSF5 (Ras association domain family member 5)
Description:
Potential tumor suppressor. Seems to be involved in lymphocyte adhesion by linking RAP1A activation upon T-cell receptor or chemokine stimulation to integrin activation. Isoform 2 stimulates lymphocyte polarization and the patch-like distribution of ITGAL/LFA-1, resulting in an enhanced adhesion to ICAM1. Together with RAP1A may participate in regulation of microtubule growth. The association of isoform 2 with activated RAP1A is required for directional movement of endothelial cells during wound healing. May be involved in regulation of Ras apoptotic function. The RASSF5-STK4/MST1 complex may mediate HRAS and KRAS induced apoptosis.
Synonyms: RAPL; NORE1; Maxp1; NORE1A; NORE1B
Tractability: Small molecule: a structure with a bound ligand is known. PROTAC: ubiquitination databases record sites on it; its protein half-life has been measured.
Gene: Protein-coding gene on chromosome 1 (206,507,531 to 206,589,448, forward strand). Ensembl gene ENSG00000266094.
Subcellular location: Cytoplasm; Cytoplasm, cytoskeleton
Gene Ontology:
Molecular function: protein binding
Biological process: signal transduction
Cellular component: nucleus; cytoplasm; cytoskeleton
Genetic constraint (gnomAD): Loss-of-function variants: 22 observed, 33.19 expected, observed/expected ratio (o/e) 0.66, 90% interval 0.47 to 0.95. The upper end of that interval is the gene's LOEUF score, 0.95, which puts it in group 4 of 6, group 1 being the genes least tolerant of losing a copy. Missense variants: 488 observed, 470.55 expected, observed/expected ratio (o/e) 1.04, 90% interval 0.96 to 1.12. Synonymous variants: 231 observed, 194.16 expected, observed/expected ratio (o/e) 1.19, 90% interval 1.07 to 1.33.
Homologues: Orthologues: chimpanzee RASSF5 (99% identical), macaque RASSF5 (97% identical), pig RASSF5 (91% identical), guinea pig RASSF5 (89% identical), dog RASSF5 (89% identical), rat Rassf5 (87% identical), mouse Rassf5 (85% identical), rabbit RASSF5 (62% identical), zebrafish rassf5 (49% identical), tropical clawed frog rassf5 (34% identical), Caenorhabditis elegans rsf-1 (30% identical), Drosophila melanogaster Rassf (13% identical). Paralogues in human: RASSF1 (35% identical), RASSF3 (26% identical), RASSF2 (16% identical), RASSF4 (15% identical), RASSF6 (15% identical).
Diseases named in the same sentence as RASSF5 in open-access papers:
RASSF5 is named in the same sentence as 43 diseases in open-access papers, as found by Europe PMC text mining. Sharing a sentence is not in itself a finding about the gene and the disease. The quoted sentences say what the papers report.
lung carcinoma (7 papers, 2008 to 2022). "Some reports have discovered the RASSF5 inactivation phenomenon in multiple human cancers, including lung cancer and gastric cancer." (PMID 36354693, 2022). "We show that upon introduction into A549 lung carcinoma cells, the engineered RASSF5 mutants decreased cell viability and mobility to a significantly greater extent than WT RASSF5." (PMID 34717958, 2021). "As a proapoptotic Ras effector, RASSF5 (NORE1A) is frequently inactivated by promoter methylation in human tumors like glioma tumor cell lines, colorectal tumors, and lung cancer." (PMID 22530128, 2012). "Besides MST1/2-mediated RASSF5 functions on cell proliferation and apoptosis, RASSF5 was also reported to function independently of ras or MST1/2 in lung cancer cells." (PMID 34681900, 2021). "Using a powerful combination of computational protein design and directed evolution, we engineered RASSF5 RA domain variants that enhance its binding affinity to Ras-GTP and Ras-GDP and demonstrate that these variants inhibit Ras-associated cancer progression in lung cancer cells." (PMID 34717958, 2021). "Indeed, we demonstrate that the engineered RASSF5 variants suppress various cancer-related processes in A549 human lung cancer cells that harbor a KRas mutant protein (G12S) and express no RASSF5." (PMID 34717958, 2021).
neuroblastoma (4 papers, 2006 to 2021). Neuroblastoma (NB) is the most common solid, extracranial childhood tumor. "The RASSF5 gene is highly methylated in numerous tumors, such as neuroblastoma, oral cancer, and liver cancer, suggesting that it may be a potential tumor suppressor." (PMID 34795691, 2021). "In the current study, we found that several of the RASSF family genes (RASSF2, RASSF4, RASSF5, RASSF6, RASSF7, and RASSF10) to various degrees were methylated in neuroblastoma cell lines and primary tumors." (PMID 22695170, 2012). "The genes RASSF5, RASSF6 and RASSF7 stand out as the most promising candidate genes for further investigations in neuroblastoma." (PMID 22695170, 2012). "RASSF5 and RASSF6 were to various degrees methylated in a large portion of neuroblastoma tumors and RASSF7 was heavily methylated in most tumors." (PMID 22695170, 2012).
colorectal cancer (3 papers, 2010 to 2022). A primary or metastatic malignant neoplasm that affects the colon or rectum. "IRF1 downregulates the RAS-RAC1 pathway by promoting the expression of RASSF5 and inhibits metastasis and proliferation of colorectal cancer cells." (PMID 36589680, 2022). "Notably, several genes such as ALX4, CHD5, MYOD1, NEUROG1, and RASSF5, whose methylation profile distinguishes this group of HCC patients from the other HCC patients, were previously reported to be similarly hypermethylated and associated with poor prognosis in colorectal cancer." (PMID 25093504, 2014).
lung adenocarcinoma (3 papers, 2017 to 2023). A carcinoma that arises from the lung and is characterized by the presence of malignant glandular epithelial cells. "For this, we selected the A549 human lung adenocarcinoma cell line for transfection since this line overexpresses an oncogenic KRas mutant (G12S) but expresses no endogenous RASSF5, thus allowing us to introduce our engineered mutants on a null background." (PMID 34717958, 2021). "In fact, in 80% of human lung adenocarcinomas Rassf5 is not expressed and was shown to be specifically silenced in lung tumor cells." (PMID 29254206, 2017).
ovarian carcinoma (3 papers, 2017 to 2021). A malignant neoplasm originating from the surface ovarian epithelium. "siRNA-mediated OIN1 silencing significantly decreased the in vivo tumor formation of ovarian cancer cells, along with the upregulation of RASSF5 and ADORA1." (PMID 34681900, 2021). "In ovarian cancer cells, RASSF5 downregulation was shown due to CpG hypermethylation in the RASSF5 promoter." (PMID 34681900, 2021). "TET1 overexpression was shown to increase RASSF5 promoter demethylation, which further stimulates RASSF5 expression, leading to the suppression of ovarian cancer cell proliferation and colony formation." (PMID 29156803, 2017). "In contrast, RASSF5 upregulation by ten-eleven translocation 1 (TET1)-mediated demethylation may result in the suppression of ovarian cancer cell proliferation." (PMID 34681900, 2021). "Up-regulated RASSF5 expression leads to the suppression of ovarian cancer cells growth." (PMID 29156803, 2017). "Notably, RNA sequencing showed that OIN1 expression was negatively correlated with the expression of apoptosis-related genes ras association domain family member 5 (RASSF5) and adenosine A1 receptor (ADORA1), which were upregulated by OIN1 knockdown in ovarian cancer cells." (PMID 34681900, 2021). "Moreover, we found that the expression of apoptosis-related genes ras association domain family member 5 (RASSF5) and adenosine A1 receptor (ADORA1) could be modulated by OIN1 in ovarian cancer." (PMID 34681900, 2021). "Additionally, to examine whether TET1 overexpression inhibits ovarian cancer growth by increasing RASSF5 levels, the effects of TET1 expression on RASSF5 levels were determined." (PMID 29156803, 2017). "Further analyses confirmed that RASSF5 expression increases in TET1-overexpressing ovarian cancer cells, but the obtained results suggested that other TET1 downstream targets may also mediate the effects of this molecule on ovarian cancer cell proliferation and colony forming ability." (PMID 29156803, 2017). "Further delineation of the mechanistic link between TET1, RASSF5, and 5hmC production should allow a better understanding of TET1 functions in ovarian cancer cells." (PMID 29156803, 2017). "Taken together, we proposed that OIN1 negatively modulates expression of RASSF5 or ADORA1, which may contribute to the alteration of ovarian cancer cell proliferation." (PMID 34681900, 2021). "A question remains how OIN1 modulates the expression of RASSF5 and ADORA1 in ovarian cancer." (PMID 34681900, 2021). "Moreover, candidate apoptosis- or cell proliferation-related genes RASSF5 and ADORA1 were identified as OIN1 downstream genes in ovarian cancer." (PMID 34681900, 2021). "For example, up-regulation of RASSF5 expression can inhibit the growth of OC cells, over-expression of FZD3 can increase the survival time of OC patients, and inhibition of MMP9 gene expression can block metastasis of ovarian cancer cells." (PMID 31182053, 2019).
breast carcinoma (2 papers, 2021 to 2023). "As for the three protective genes, the prognostic value of FERMT3 and RASSF2 has been noted in breast cancer, while that of RASSF5 has not." (PMID 34604090, 2021).
Disc Degeneration (2 papers, 2023 to 2024). "Studies have shown that miR-27a-3p ameliorates disc degeneration by targeting RASSF5, and RASSF5 promotes apoptosis and inhibits the proliferation of nucleus pulposus cells." (PMID 39726744, 2024).
liver cancer (2 papers, 2012 to 2021). An epithelial or non-epithelial malignant neoplasm that arises from the liver. "As concerns RASSF2, RASSF4, and RASSF5 isoforms (NORE1A and NORE1B), promoter hypermethylation seems to be the prominent mechanism responsible for their inactivation in liver cancer." (PMID 22548173, 2012). "Altogether, the data indicate that inactivation of the RASSF1A tumor suppressor is ubiquitous in human liver cancer, while downregulation of RASSF2 and RASSF5 proteins is limited to specific HCC subsets." (PMID 22548173, 2012). "Also, the present findings speak in favour of therapeutic strategies aimed at reexpressing RASSF1A, RASSF2, and RASSF5 genes and/or inactivating the RASSF cellular inhibitors for the treatment of human liver cancer." (PMID 22548173, 2012).
oral cancer (2 papers, 2021). "miR-214 expression was observed to be elevated and RASSF5 was down-regulated in oral cancer cell lines." (PMID 33806361, 2021). "Moreover, miR-214 regulated KB cell apoptosis through targeted inhibition of RASSF5 expression, FOXO3a phosphorylation, and BIM expression, suggesting its plausible application as a novel therapeutic oral cancer target." (PMID 33806361, 2021).
thyroid cancer (2 papers, 2010 to 2020). "Collectively, our findings clarify that MAPK8IP1P2 activates Hippo signaling by sponging miR-146b-3p to disrupt the inhibitory effect of miR-146b-3p on NF2, RASSF1, and RASSF5 expression in thyroid cancer." (PMID 33489905, 2020). "In the current study, our results showed that MAPK8IP1P2 activated Hippo signaling by sponging miR-146b-3p to disrupt targeting effect of miR-146b-3p on NF2, RASSF1, and RASSF5, which inhibited anoikis resistance and lymphatic metastasis of thyroid cancer." (PMID 33489905, 2020). "Mechanistically, MAPK8IP1P2 activated Hippo signaling by sponging miR-146b-3p to disrupt the inhibitory effect of miR-146b-3p on NF2, RASSF1, and RASSF5 expression, which further inhibited anoikis resistance and lymphatic metastasis in thyroid cancer." (PMID 33489905, 2020). "Overexpression of miR-146b-3p directly targeted NF2, RASSF1, and RASSF5 in thyroid cancer cells and inactivated Hippo signaling, which further promoted anoikis resistance and lymphatic metastasis of thyroid cancer." (PMID 33489905, 2020). "Mechanistic investigations revealed that MAPK8IP1P2 activated Hippo signaling by sponging miR-146b-3p to disrupt the inhibitory effect of miR-146b-3p on NF2, RASSF1, and RASSF5 expression, which further inhibited anoikis resistance and lymphatic metastasis in thyroid cancer." (PMID 33489905, 2020). "In summary, our results demonstrate that MAPK8IP1P2 activates Hippo signaling by sponging miR-146b-3p as a ceRNA to disrupt the inhibitory effect of miR-146b-3p on NF2, RASSF1, and RASSF5 expression, which further suppresses lymphatic metastasis of thyroid cancer." (PMID 33489905, 2020). "Epigenetic inactivation of RASSF5 in thyroid cancer has also been investigated." (PMID 20920251, 2010). "Epigenetic silencing of RASSF5 in thyroid cancer has been analyzed previously, but was also not tumor specific." (PMID 20920251, 2010). "Importantly, miR-146b-3p mimics not only reversed the NF2, RASSF1, and RASSF5 level enhanced by MAPK8IP1P2 overexpression, but also inactivated Hippo signaling in MAPK8IP1P2-overexpressing thyroid cancer cells as indicated by elevated the luciferase reporter activity of HOP-Flash." (PMID 33489905, 2020).
bladder cancer (1 paper, 2012). "We studied DNA promoter methylation of five RASSF family members (RASSF1A, RASSF2A, RASSF4, RASSF5, and RASSF6) in FFPE bladder cancer tissues and normal adjacent tissues." (PMID 22530128, 2012).
Epileptic encephalopathy (1 paper, 2018). A condition in which epileptiform abnormalities are believed to contribute to the progressive disturbance in cerebral function. "The top-ranked probes related to 25 genes including HNRNPL, RASSF5, CD3D and KALRN involved in immune signalling pathways, in addition to TBC1D24, FBXO9 and VIPR2 previously linked to epileptic encephalopathy." (PMID 29484035, 2018).
head and neck squamous cell carcinoma (1 paper, 2021). A squamous cell carcinoma that arises from any of the following anatomic sites: lip and oral cavity, nasal cavity, paranasal sinuses, pharynx, larynx, and salivary glands. "Notably, Rassf5 is methylated in the majority of esophageal and head and neck squamous cell carcinomas and has been shown to inhibit Ras growth via senescence and apoptosis." (PMID 33393458, 2021).
Hypertension (1 paper, 2024). The presence of chronic increased pressure in the systemic arterial system. "Moreover, the methylation of cg20305610 and cg24450312 was also associated with increased risk of incident NAFLD, and their related PDLIM5 and RASSF5 genes have been reported to correlate with obesity, type 2 diabetes, and hypertension previously." (PMID 37605101, 2024).
ischemic stroke (1 paper, 2024). A stroke disorder caused by obstruction of blood flow to the brain, due to thrombotic (local blood clot formation) or embolic (due to a blood clot or other material traveling from another site) event. "Implications of the SNHG10/miR-665/RASSF5/NF-κB pathway in dihydromyricetin-mediated ischemic stroke protection." (PMID 39726744, 2024). "Our findings reveal a novel regulatory axis, SNHG10/miR-665/RASSF5, which modulates neuroinflammation and oxidative stress in ischemic stroke, suggesting this axis as a promising therapeutic target." (PMID 39726744, 2024). "In conclusion, this study provides significant insights into the neuroprotective mechanisms of DHM in ischemic stroke, particularly through modulation of the SNHG10/miR-665/RASSF5 axis." (PMID 39726744, 2024).
myeloid leukemia (1 paper, 2023). A clonal proliferation of myeloid cells and their precursors in the bone marrow, peripheral blood, and spleen. "Here, we define another mechanism for decreased RASSF5 transcription; decreased Irf8 expression as found in myeloid leukemias or with aging." (PMID 37247756, 2023).
non-small cell lung carcinoma (1 paper, 2025). A group of at least three distinct histological types of lung cancer, including non-small cell squamous cell carcinoma, adenocarcinoma, and large cell carcinoma. "For instance, in copy number omics, we discover pathways corresponding to genes like EGFR, CDK6, RASSF5, BRAF, and CCND1, which are associated with non-small cell lung cancer." (PMID 40191608, 2025).
pancreatic cancer (1 paper, 2014). "The inactivation of the RAS-associated RASSF1A and RASSF5 complexes, which act as tumour suppressors, is frequent in pancreatic cancer." (PMID 25521701, 2014).
somatotroph adenoma (1 paper, 2013).